CXCL13 (C-X-C motif chemokine ligand 13)
Diseases named in the same sentence as CXCL13 in open-access papers (continued):
Sharing a sentence is not in itself a finding about the gene and the disease.
cancer (continued). "Notably, genes upregulated in CXCL13+ exhausted T cells (CXCL13+ Tex) were enriched in responder-associated pathways such as PD-L1 expression and PD-1 checkpoint pathway in cancer and TCR signaling pathway for CD8+ T cell subtypes." (PMID 41045934, 2025). "CXCL13 expression levels were found to be associated with these immune infiltrates in this study, which is consistent with a previous study, making it a potential biomarker for different cancer prognosis and immunotherapy outcomes." (PMID 40076932, 2025). "Cancer-associated fibroblasts (CAFs) exhibit elevated expression levels of CXCL13, BAFF, and APRIL." (PMID 41285707, 2025). "Indeed, CXCL13 is statistically significantly more strongly associated with interval compared to screen-detected cancer in a case-only analysis (P = 0.005)." (PMID 38135714, 2024). "Moreover, CXCL10 and CXCL13 have both been linked to cancer progression and an unfavorable clinical course in colorectal carcinoma and HCC patients." (PMID 36077611, 2022). "CXCL13 is crucial for the homing and motility of B cells in lymphoid tissue and has been implicated in the formation of ectopic lymphoid tissue in chronic inflammation and cancer." (PMID 33841320, 2021). "Previous studies have shown that CXCL13 is associated with the prognosis of various cancers." (PMID 34631779, 2021). "(2018), and taken together, highlights that CXCL13 expression may be a feature of clonal neoantigen-reactive CD8 TILs that associates with CPI outcome in a pan-cancer cohort." (PMID 33508232, 2021). "Similarly, in the neoadjuvant GeparSixto trial a high cancer CXCL13 mRNA content was associated with a high pCR rate." (PMID 29482642, 2018). "Therefore, relying solely on the individual test value of CXCL13 to assess cancer risk may be inadequate." (PMID 39344390, 2024). "Notably, we observed that the interaction between HLA-E and NKG2A (either alone or in a complex with CD94), which is associated with T cell inhibition and increased cancer growth, was enriched in CXCL13+ CD8+ TRMs interacting with epithelial cells at CC tissues." (PMID 39014148, 2024). "Moreover, high CXCL13 expression was associated with advanced stage cancer and poor prognosis." (PMID 26565418, 2015). "In lung adenocarcinoma, pulmonary TLSs that contain GCs are CXCL13‐dependent and generate cancer‐specific antibodies against endogenous retroviruses that are expressed by the cancerous cells." (PMID 40884054, 2025). "Specifically, CXCL13 was previously analyzed in a single-cell meta-analysis across five cancer types and was found to be correlated with a favorable response to ICI treatment." (PMID 40187353, 2025). "Based on these results, we concluded that CXCL13 + CD8 + T cells are the main type of CTL that directly attacks cancer cells in the environment after treatment with anti-PD-L1-CRT." (PMID 40670667, 2025). "The genetic characterization of 12 chemokines in TLS, particularly CCL19, CCL21, and CXCL13, has been linked to increased survival in patients with BC, CRC, and other cancers." (PMID 40038799, 2025). "This distinction highlights the dual role of the immune microenvironment in cancer, in which CXCL13 enhances immune surveillance, while LDHA contributes to immune evasion." (PMID 40260244, 2025). "The CXCL13/CXCR5 axis was reported to be involved in regulating cancer cell migration and shaping an immunosuppressive TME, highlighting its potential as a prognostic biomarker and therapeutic target." (PMID 40943634, 2025). "For quantitative assessment, we selected four tissue sections each for CXCL13 co-staining with CD4+ T cells, CD8+ T cells, and cancer-associated fibroblasts (CAFs)." (PMID 40352278, 2025). "Analysis of mouse plasma revealed increased secretion of cancer-related proteins, such as CXCL13, CXCL16, MMP2, selectins, and pentraxin 2, in the group with MCPIP1 mutations." (PMID 39815326, 2025).
cancer (continued). "Proteomic analysis of mouse plasma revealed increased secretion of cancer-related proteins (CXCL13, CXCL16, and MMP2) in the MCPIP1-mutant group." (PMID 39815326, 2025). "Cluster 5 consisted of cancer-associated fibroblasts (CAFs), CD14+ monocytes, CXCL13+ CD4+ follicular helper cells, and GZMA+ CD4+ memory/effector T cells." (PMID 41279139, 2025). "Previous studies have highlighted the differential expression patterns of HAVCR2, TIGIT, LAG3, LAYN, and CXCL13, showing strong correlations with survival outcomes across multiple cancer types." (PMID 40076932, 2025). "To assess their function in cancer, we used Pf4creCx3cr1DTR mice, which predominantly deplete CD206hi IMs, including those that express Cxcl13 (for B cell chemotaxis), Cxcl9 and Cxcl10 (for NK and T cell recruitment), as well as Ccl6, Ccl8, Ccl9, and Ccl2418." (PMID 40630529, 2025). "A cancer microenvironment enriched with CXCL13 elicits the recruitment of CXCR5-expressing leukocytes." (PMID 40548381, 2025). "In diseases other than RA, CXCL13 has been reported to be produced by Tph cells in the intestine of ulcerative colitis (UC) and in malignant tumors." (PMID 37788648, 2024). "Violin plots show that expression of CXCL13 was significantly higher in tumors compared to the para-cancerous/normal tissues, and similar conclusions were obtained at the pan-cancer level." (PMID 38459390, 2024). "We initially explored the expression of the Tex signature genes (LAG3, TIGIT, LAYN, PDCD1, HAVCR2, and CXCL13) in pan-cancer." (PMID 39064019, 2024). "Previous studies demonstrated that the B-cell chemoattractant CXCL13 was recently found to be associated with the CXCR5+ T follicular helper cell (TFH cell) infiltration and improved survival in human cancer." (PMID 39001456, 2024). "Collectively, these findings suggest a relationship between upregulated CXCL13 expression and poor prognosis in various types of cancer." (PMID 39344390, 2024). "Chemokines CCL7, CCL24, and CXCL13, as well as IL-10 and Bmp2, exert pro-tumorigenic effects in a variety of cancers, promoting the invasiveness, metastasis, and stemness of cancer cells." (PMID 38892209, 2024). "In cancer, it also plays a major role in the recruitment of B cells to TLSs, yet the potential effect of CXCL13 in the TME as a predictive prognostic biomarker is controversial." (PMID 38398098, 2024). "CXCL13 expression has been reported to hold pro-tumorigenic roles in cancers such as central nervous system lymphoma, follicular lymphomas, and colon carcinoma." (PMID 39409924, 2024). "Second, CXCL13 has been reported to be highly expressed by neoantigen-reactive CD8+ T cells directly involved in cancer cell killing." (PMID 38722600, 2024). "Inhibitor targeting the CXCL13/CXCR5 axis was demonstrated to have an encouraging effect on cancer treatment." (PMID 36816030, 2023). "Given the central role of PD-1 inhibition in cancer immunotherapy, this also pertains to PD-1-expressing components of the CXCL13/CXCR5-axis." (PMID 36836910, 2023). "The presence of CXCL13-producing CD4+ T cells and the formation of TLSs were associated with improved survival in patients with several malignant tumors." (PMID 37762313, 2023). "It is notable that CXCL13 is also the key component of various TLS gene signatures reported in different types of cancers." (PMID 36453453, 2023). "Among them, we selected Il-21, Cxcl13, Cdk6, Cdk1, and Cxcr7, all cytokine, cell cycle, or cancer-related genes." (PMID 37304286, 2023). "CXCL13+ TILs represented only a median of 1% of total TILs and were similarly expressed in all cancer subtypes." (PMID 37835488, 2023). "CXCL13, a well-known marker of inflammation in cancer and CNS infections, has been suggested as a potential prognostic biomarker for MS, as its levels are extremely high in patients with this clinically unpredictable disease." (PMID 37446228, 2023).
cancer (continued). "Among the genes selected to construct the NR-signature, VSIG4, SIGLEC1, and CXCL13 showed significant correlations with immune microenvironment scores in pan-cancer." (PMID 36544770, 2022). "The gene expression data suggests an important role for CXCL13 that was the most highly and consistently overexpressed chemokine in cancers from younger women." (PMID 36344517, 2022). "The CCL4/CCR5 axis, CXCL9/CXCR3-axis, and CXCL13/CXCR5-axis have previously been shown to promote cancer progression and metastasis." (PMID 36163179, 2022). "We also examined CXCL13 protein levels in different cancer types using the immunohistochemistry results from ‘The Human Protein Atlas’ database." (PMID 35141160, 2022). "CXCL13 expression levels were positively related to TMB in 5 cancer types (UCEC, KICH, OV, CESC, and COAD) but negatively related to TMB in 6 different cancer types, including HNSC, TGCT, KIRP, PAAD, MESO and THCA." (PMID 35141160, 2022). "The present study used multilevel data to elucidate the CXCL13 expression-based panoramic picture in human cancer to clarify its likely role in cancer development, progression, and immunity." (PMID 35141160, 2022). "CXCL13 expression was able to predict the response to ICI by directly or indirectly influencing the responses of various cancer types." (PMID 35053457, 2022). "In cancer cells, CXCL13/CXCR5 regulates cell invasion and migration, and those are in Gαq and Gαi2 /Rac dependent manner." (PMID 35053457, 2022). "In short, genetic changes play an important part in regulating CXCL13 expression and prognosis of cancer patients, the regulation mechanisms deserve more comprehensive investigation." (PMID 35141160, 2022). "TGFβ was shown to induce CXCL13 expression in PD-1highCD4+ cells under inflammatory conditions and in cancer." (PMID 36217194, 2022). "Meanwhile, we have explored the correlation between CNV of CXCL13 and the overall survival of cancer patients." (PMID 35141160, 2022). "CXCL13/CXCR5 signaling axis modulated cancer cell ability to grow, proliferate, invade, and metastasize." (PMID 36032660, 2022). "T cells follicular helper, characterized by the expression of CXC chemokine receptor 5 (CXCR5), are positively connected with survival of cancer patients by the immunoprotective functions of CXCL13 which is correlated with CXCR5 in germinal center." (PMID 36397112, 2022). "In lymphoid organs as well as cancers, Tfh cells are important regulators of antigen-specific B cell responses, since they produce the B cell chemoattractant CXCL13 to which B cells respond through its receptor CXCR5." (PMID 36077836, 2022). "In response to combinatory therapy, cancer cells are subject to apoptosis when exposed to CXCL13+ T cells." (PMID 35392977, 2022). "The autoreactivity-induced deregulation of CXCL13 in BC reported here supports existing work reporting on chronic inflammation and cancer development." (PMID 37082114, 2022). "Intriguingly, utilizing intrakine CXCL13-KDEL, which traps CXCR5 in the endoplasmic reticulum, causes a prolonged growth arrest of cancer cells." (PMID 34947813, 2021). "CXCL13 has been shown to control the phenotype of cancer cells in various solid tumors and to affect the migration, invasion, and growth of cancer cells." (PMID 35047401, 2021). "Signaling via the CMS1-associated CXCL13, and its receptor CXCR5, has been shown to induce cancer progression through PI3K, Akt, ERK 1/2, and Jun." (PMID 34830978, 2021). "In this review, we summarize the molecular events and TME alterations caused by CXCL13/CXCR5 and briefly discuss the potentials of agents targeting this axis in different malignant tumors." (PMID 34947813, 2021). "The prognostic impact of CXCL13 is still controversial, probably because CXCL13 plays a distinct role depending upon the cancer type." (PMID 33506656, 2021).
cancer (continued). "Lastly, we show with single-cell RNA-seq that CXCL13, a marker of exhausted T cells in multiple human cancers, is preferntially expressed in both T cells reactive to a clonal neoantigen and responders in the CPI1000+ cohort." (PMID 33508232, 2021). "Compared with the expression levels in normal samples, ITLN1, TSPAN11, CPRC5B, and CXCL13 showed significantly low expression levels in most cancer types, including COAD, while TIMP1 was expressed highly in most cancer types." (PMID 33579281, 2021). "The role of the CXCL13/CXCR5 pathway in the cancer stem cells of other malignancies remains to be investigated." (PMID 34947813, 2021). "The expression levels of six chemokine genes (CCL5, CXCL9, CXCL13, CXCL10, CXCL11, and CCL19) were significantly associated with the image-based immune scores across all 13 tested cancer types." (PMID 34030676, 2021). "In a variety of malignant tumors, CXCL13 interacts with its receptor CXCR5 to promote carcinogenesis, development, and metastasis." (PMID 34922542, 2021). "In recent years, the infiltration of Tfh cells was discovered to correlate positively with better prognosis in patients with malignant tumors, which mainly depended on the recruitment of C-X-C motif chemokine ligand 13 (CXCL13) to CD8+ T cells and B cells." (PMID 34359579, 2021). "CXCL13, on the other hand, has been shown in certain studies to prevent the occurrence and growth of malignant tumors." (PMID 34922542, 2021). "CCL5, CXCL9, CXCL13, CXCL10, and CXCL11 were also among the top chemokine genes associated with the gene expression-based immune scores across multiple cancer types." (PMID 34030676, 2021). "Previous studies demonstrated that CXCL13 upregulation was regarded as a biomarker for poor prognosis in various cancers, including ccRCC 50-52." (PMID 32669964, 2020). "In this article, we comprehensively review the involvement of the chemokine C-X-C motif ligand 13 (CXCL13) in cancer progression, focusing primarily in novel aspects of CXCL13 biology in solid tumors." (PMID 31354634, 2019). "CXCL13 also seems to play a prominent role in the development of pancreatic adenocarcinoma, one of the most aggressive and incurables forms of cancer." (PMID 31354634, 2019). "In this review, we provide a comprehensive perspective of the involvement of CXCL13 and its receptor in cancer progression." (PMID 31354634, 2019). "CXCL13:CXCR5 axis is involved in many biological responses in immune cells as well as in cancer cells, as described in subsequent sections." (PMID 31354634, 2019). "New discoveries in the CXCL13:CXCR5 field would also aid clinical decision-making for cancer patients, bringing us closer to the promise of translational precision medicine." (PMID 31354634, 2019). "The prognostic effect of cancer CXCL13 content was most pronounced in the subset of patients with TNBC." (PMID 29482642, 2018). "In total, 10 proteins had an estimated AUC of at least 0.7 and were significantly associated with cancer status, including hK11, PRSS8, IL-6, MK, and CXCL13." (PMID 29051715, 2017). "From the clinic samples to cancer cell lines, CXCL13 is higher expressed in PCa tissues and PCa cells than that in Pericarcinomatous tissues and normal prostate cells (WPMY-1 cells)." (PMID 28881808, 2017). "Recent studies revealed that Snail played an important role in chemoresistance, further, it was also reported that chemokines such as CXCL13 treatment can upregulate the expression of Snail in cancer cells and induce EMT." (PMID 27057280, 2016). "Because the chemokine receptor CXCR5 and its ligand CXCL13 are unique and exclusive to each other, we assessed the role of CXCR5-CXCL13 signaling in MDSC migration towards cancer cells." (PMID 26462153, 2015). "At least two tumors were found in left and/or right lungs of each BaP-treated mouse, and CXCL13 induced cancer cell migration and metastasis." (PMID 26565418, 2015).
cancer (continued). "This view is also supported by a recent study demonstrating a growth advantage of CXCR5-positive cancer cells within the liver of mice presumably through CXCL13 produced by liver cells in their microenvironment." (PMID 18781150, 2008). "As a chemokine, CXCL13 plays a significant role in cancer cell biology." (PMID 40692663, 2025). "Additionally, we discovered that CXCL13 + T cells directly impact cancer cells in the posttreatment environment." (PMID 40670667, 2025). "We identified a higher proportion of CXCL13+ T cells in non-recurrent tumors and investigated their interactions with myeloid cells and cancer associated fibroblasts to uncover potential mechanisms underlying recurrence." (PMID 40464813, 2025). "In our study, we find that CXCL13 alone is not sufficient to predict prognosis, but the situation may vary in other types of cancers, indicating extensive research prospects for CXCL13." (PMID 38459390, 2024). "However, in the era of scRNA-Seq, key cell subpopulations in the TME were identified to be essential for the immunotherapy response, and CXCL13+ T cells emerged as one of the most important T lymphocyte subgroups in cancer immunotherapy." (PMID 38478516, 2024). "In TA-TLSs, the origin of CXCL13 depends on the type of cancer." (PMID 39569184, 2024). "Previous studies showed that CXCL13+ T cells could advance the development of early TLSs in cancers." (PMID 38478516, 2024). "Therefore, all these findings suggest CXCR5 and CXCL13 as good prognostic markers of TILs against cancer cells as both confirmed in animal and human studies associated with a better clinical outcome." (PMID 39001456, 2024). "CXCL13 has been identified as one of the most potent predictors of improved survival in human cancers, and the production of CXCL13 by T cells infiltrating inflammatory tissues may be a critical step in the initiation of TLSs formation." (PMID 38628669, 2024). "Blocking CXCL13 signaling may therefore be a target to improve morphine analgesia in patients with cancer pain." (PMID 38940936, 2024). "Similarly, estimated TLS ratios significantly correlated with B cell levels and CXCL13 expression in these cancers, suggesting broad applicability of our approach." (PMID 38519580, 2024). "Moreover, elevated CXCL13 expression levels have been observed in several types of cancers, such as breast, prostate, and gastrointestinal cancers." (PMID 39344390, 2024). "CXCR5 has previously been employed to increase CAR-T cell infiltration into CXCL13+ cancers." (PMID 39450160, 2024). "Finally, we gathered the IC50 of a wide variety of drugs among different cancer cell lines through the GDSC and CTRP databases and tried to explore the possible associations with the corresponding CXCL13, HAVCR2, LAG3, TIGIT, PDCD1, and LAYN mRNA values." (PMID 39064019, 2024). "CXCL13 expression was positively correlated with CD8+ T cell percentage in most cancer types." (PMID 37540227, 2023). "Importantly, the key effector cells of the CXCL13/CXCR5-associated immune axis express PD-1, hence attracting increasing interest as secondary or ancillary targets of anti-PD-1 therapy in different cancer types." (PMID 36836910, 2023). "On the one hand, the CXCL13 signal plays a leading role in the recruitment of B cells and the formation of tertiary lymphoid structures, activating the immune response of some tumors; on the other hand, CXCL13 is critical for driving the occurrence, development, and metastasis of malignant tumor." (PMID 37675100, 2023). "As a specific receptor of CXCL13, CXCR5 mediates cancer functions regulated by CXCL13." (PMID 35978426, 2022). "When the PD-1/PD-L1 signal was inhibited, CXCL13 produced by ASPH+ cancer cells recruited CXCR5+/CD8+ T lymphocytes to tertiary lymphoid structures (TLSs), comprising effector and memory CTLs, T follicular helper cells, B cell germinal center, and follicular dendritic cells." (PMID 35392977, 2022).